H19 (H19 imprinted maternally expressed transcript)
Diseases named in the same sentence as H19 in open-access papers (continued):
Sharing a sentence is not in itself a finding about the gene and the disease.
adenomyosis (2 papers, 2025). The growth of endometrial tissue inside the muscular wall of the uterine corpus. "The regulatory role of miR-17 in adenomyosis, particularly via the lncRNA H19/miR-17/TLR4 pathway, has been previously established." (PMID 41374393, 2025). "In fibroids, H19 overexpression drives ECM accumulation via TGF-β and collagen regulation, whereas in adenomyosis, H19 acts primarily through inflammatory derepression (via miR-17 → TLR4/NF-κB)." (PMID 41226749, 2025).
adrenal tumors (2 papers, 2015 to 2023). "28/38 adrenal tumors with LOH of the IGF2/H19 locus had lost the maternal allele and gained an extra copy of the paternal allele." (PMID 26400872, 2015). "Our data provide conclusive evidence that loss of the maternal allele correlates with IGF2 overexpression in adrenal tumors and that hypermethylation of the H19 ICR is a consequence thereof." (PMID 26400872, 2015). "In conclusion, our data suggest that IGF2 overexpression in adrenal tumors correlates mainly with allelic loss leading to an imbalance of the ratio between paternal and maternal alleles and that the aberrant DNA methylation levels observed for the H19 ICR are a consequence thereof." (PMID 26400872, 2015). "Gene expression changes of IGF2 and H19 were analyzed in 60 fresh frozen adrenal tumors." (PMID 26400872, 2015). "In the current study, we provide the first integrated analysis of gene expression, DNA methylation and genetic variation of the IGF2/H19 locus in adrenal tumor subtypes using high-resolution molecular technologies to unravel the driving force behind IGF2 overexpression in these tumors." (PMID 26400872, 2015). "In the present study we therefore integrated IGF2 and H19 expression levels with the DNA methylation levels of three regulatory DMRs located throughout the IGF2/H19 locus and compared this to the copy number status and ploidy of chr11p15.5 in a cohort of 62 adrenal tumor samples." (PMID 26400872, 2015).
amyotrophic lateral sclerosis (2 papers, 2023 to 2024). Amyotrophic lateral sclerosis (ALS) is a neurodegenerative disease characterized by progressive muscular paralysis reflecting degeneration of motor neurons in the primary motor cortex, corticospinal tracts, brainstem and spinal cord. "For instance, lncRNA H19 is significantly upregulated in denervation-induced muscle atrophy, the late phrase of amyotrophic lateral sclerosis, as well as in COPD patients with a low fat-free mass index and low muscle strength." (PMID 37344807, 2023).
anaplastic thyroid carcinoma (2 papers, 2019 to 2022). "The present study was performed to determine the expression levels of H19 in anaplastic thyroid carcinoma (ATC) tissues and the role of H19 in ATC 8505C cells in vitro and in vivo." (PMID 31299871, 2019).
ankylosing spondylitis (2 papers, 2021 to 2024). An autoimmune chronic inflammatory disorder characterized by inflammation in the vertebral joints of the spine and sacroiliac joints. "One of the major findings of this review is the frequent association of the H19 lncRNA with vitamin-driven regulation in disease, spanning disorders from Ankylosing Spondylitis to a range of cancers." (PMID 38475720, 2024). "Two H19-dependent regulatory axes together affect the expression of VDR and increase the inflammatory response in Ankylosing Spondylitis (AS)." (PMID 38475720, 2024).
aortic stenosis (2 papers, 2019 to 2025). Aortic valve stenosis is a aortic valve disease caused by the incomplete opening of the aortic valve. "In this study, we examined the effect of age and sex on epigenetic dysregulation of H19 and subsequent aortic stenosis." (PMID 31609547, 2019). "Despite the lack of strong H19 upregulation, a few of the oldest mice showed signs of early aortic stenosis as indicated by elevated PSV and transvalvular pressure gradient." (PMID 31609547, 2019).
aortic valve diseases (2 papers, 2018 to 2022). "H19 has been demonstrated to be involved in cardiovascular diseases like aortic valve diseases." (PMID 35198556, 2022). "It is reported that epigenetic-related dysregulation of H19 may play complex roles in different disorders, including stenotic aortic valves disease." (PMID 30241458, 2018).
arterial disease (2 papers, 2019 to 2021). "Multiple studies showed that H19 is high-expressed in human and mouse AAAs, suggesting that H19 may play an important role in arterial disease." (PMID 33403385, 2021).
Arthritis (2 papers, 2020 to 2022). Inflammation of a joint. "As an example, lncRNA H19 promotes M1 macrophage polarization and aggravates arthritis by upregulating KDM6A expression, which contradicts the role of H19 in promoting M2 polarization through the H19-miR let-7a/c-Myc axis in IPF." (PMID 36685535, 2022). "Additionally, H19 overexpression promoted M1 macrophage polarization along with increased expression of M1 macrophage-related factors and aggravated arthritis in mice by upregulating KDM6A expression." (PMID 36685535, 2022). "In summary, the role of H19 in arthritis is inflammation-related." (PMID 33193379, 2020). "H19 may contribute inflammation development in arthritis through interacting with the canonical inflammation pathway." (PMID 33193379, 2020).
atrophic gastritis (2 papers, 2020 to 2022). "According to our verified experiments of differential lncRNAs, the expression level of lncRNA H19 in the GC group was significantly higher than that in the chronic non-atrophic gastritis group, which was consistent with the results of previous studies." (PMID 35571069, 2022).
Atrophy (2 papers, 2019 to 2023). Any weakening or degeneration, especially through lack of use. "We further defined the role of lncRNA H19/miR-675 in inducing muscle atrophy by targeting IGF1R, which provides clues for further elucidation of the mechanism of muscular atrophy and potential therapeutic targets." (PMID 37344807, 2023). "We found that 2310065F04Rik (linc-Myh) resulted down-regulated in both atrophy models while Dancr, Gas5, H19, Igf2os, Airn, MiR22hg, Neat1 and Snhg1 were up-regulated in the late phases of atrophy." (PMID 30649422, 2019). "The lncRNA H19/miR-675 axis can induce muscle atrophy, and its downregulation in mice with HS-induced muscle atrophy may act as a protective mechanism against this condition." (PMID 37344807, 2023).
Azoospermia (2 papers, 2014 to 2021). Absence of any measurable level of sperm,whereby spermatozoa cannot be observed even after centrifugation of the semen pellet. "Early orchidopexy did not rescue his azoospermia, which might be not the consequence of cryptorchidism, but due to genetic defects associated with H19 deletion." (PMID 33679886, 2021).
bone tumor (2 papers, 2017 to 2020). "lncRNAH19 may be essential for BMP9-induced osteogenic differentiation of MSCs, and the dysregulation of H19 expression may impair normal osteogenesis, leading to pathogenic processes such as bone tumor development." (PMID 32528134, 2020). "Our findings suggest that the well-coordinated biphasic expression of lncRNA H19 may be essential in BMP9-induced osteogenic differentiation of MSCs, and that dysregulated H19 expression may impair normal osteogenesis, leading to pathogenic processes, such as bone tumor development." (PMID 28881833, 2017).
bronchopulmonary dysplasia (2 papers, 2020 to 2024). Bronchopulmonary dysplasia is a chronic respiratory disease that results from complications related to lung injury during the treatment of infant acute respiratory distress syndrome in low-birth-weight premature infants or from abnormal lung development in older infants. "lncRNA H19 can promote the development of bronchopulmonary dysplasia by regulating the MAPK signaling pathway, and the MAPK signaling pathway can be used as a potential target for the treatment of bronchopulmonary dysplasia." (PMID 32855971, 2020).
clear cell renal carcinoma (2 papers, 2017 to 2022). A malignant epithelial neoplasm of the kidney characterized by the presence of lipid-containing clear cells within a vascular network. "The research find that relative level of H19 is significantly higher in clear cell renal carcinoma (ccRCC) compared to the adjacent normal renal tissues." (PMID 34983363, 2022). "Our result was consistent with other study and cell proliferation of clear cell renal cell carcinoma cells was significantly reduced at the different indicated time points with si-H19." (PMID 29214011, 2017). "E2F1 plays a vital role in cell proliferation, it is unclear whether lncRNA H19 has effects on proliferation of clear cell renal cell carcinoma cells." (PMID 29214011, 2017).
cleft palate (2 papers, 2018 to 2019). Cleft palate is a fissure type embryopathy that affects the soft and hard palate to varying degrees. "Other studies, in rodents, of reproductive toxicity have shown TCDD exposure of pregnant animals to be associated with H19-mediated cleft palate, as well as with H19-mediated ovarian toxicity." (PMID 31665024, 2019). "Therefore, lncRNA H19 is suggested to be the primary contributor to the development of cleft palate induced by TCDD." (PMID 30567322, 2018).
colorectal tumor (2 papers, 2018 to 2019). "Patients with high CSRP2 expression in colorectal tumours, display significantly shorter overall survival, and combined analysis of H19 with CSRP2 appears to be a powerful prognostic factor for overall survival." (PMID 29976963, 2018). "Besides the ones that were reported to be dysregulated in colorectal tumor samples, such as CCAT1, H19, DANCR, ZFAS1, SNHG16, CYTOR, we have identified many others in this study including LUCRC." (PMID 32082365, 2019).
coronary atherosclerosis (2 papers, 2021). Atherosclerosis of the coronary vasculature. "For example, LncRNA ANRIL, and lncRNA H19 are strongly associated with the risk of developing coronary atherosclerosis." (PMID 34235188, 2021). "In addition, cyclin-dependent kinase inhibitor 2B antisense RNA1 (ANRIL) may prevent coronary atherosclerosis, and increased plasma levels of the lncRNAs H19 and LIPCAR are linked to increased risk of CAD." (PMID 34369281, 2021).
dilated cardiomyopathy (2 papers, 2017 to 2022). Cardiomyopathy which is characterized by dilation and contractile dysfunction of the left and right ventricles. "In a rat model of adriamycin-induced dilated cardiomyopathy, H19 expression was increased and its suppression attenuated CM apoptosis and improved left ventricular function." (PMID 35946958, 2022). "While 8 weeks HFD also suppressed H19 levels, adriamycin-induced dilated cardiomyopathy seems to give a different response, where increased expression of H19 was observed after 3 weeks and its down-regulation attenuated CM apoptosis and improved left ventricular function." (PMID 35946958, 2022). "In the previous study, we generated a rat model of dilated cardiomyopathy (DCM) induced by adriamycin and found that the expression of lncRNA H19 was significantly upregulated in myocardial tissue." (PMID 28430627, 2017).
diphtheria (2 papers, 2020 to 2025). A Gram-positive bacterial infection caused by Corynebacterium diphtheriae. "BC-819, also known as H19-DTA, is a DNA vector that encodes for Diphtheria Toxin A fragment (DTA) under the control of H19 gene promoter (BC-819 or DTA-H19), whereas PEI is a transfection agent." (PMID 32854207, 2020). "BC‐819 (inodiftagene vixteplasmid), or DTA‐H19, is a plasmid DNA with Diphtheria Toxin A regulated by the H19 promoter combined with polyethylenimine (PEI) that selectively targets urothelial carcinoma cells through H19 promoter overexpression." (PMID 40948378, 2025).
dysplasia (2 papers, 2015 to 2023). A usually neoplastic transformation of the cell, associated with altered architectural tissue patterns. "Downmodulation of lncRNA H19 has also been strongly linked to the occurrence of dysplasia and the progression of hip dislocation." (PMID 36787444, 2023). "The plasma H19 levels were significantly higher in dysplasia patients (p = 0.000)." (PMID 26096073, 2015).
endothelial dysfunction (2 papers, 2019 to 2025). In vascular diseases, endothelial dysfunction is a systemic pathological state of the endothelium (the inner lining of blood vessels) and can be broadly defined as an imbalance between vasodilating and vasoconstricting substances produced by (or acting on) the endothelium. "In this study, we show that H19/miR-29b/VEGFA signaling pathway plays a role in hyperglycemic-induced endothelial dysfunction." (PMID 31737629, 2019). "We found a novel pathogenic link between lncRNA H19, miR-29b, and VEGFA in hyperglycemic-induced endothelial dysfunction." (PMID 31737629, 2019). "For example, we have shown in DR, that ANRIL regulates VEGF, H19 inhibits inflammatory responses and prevents endothelial dysfunction, HOTAIR promotes angiogenesis, oxidative stress and mitochondrial dysfunction, and MALAT1 regulates inflammation via modulation of epigenetic regulators." (PMID 40271126, 2025).
gastric adenocarcinoma (2 papers, 2021 to 2022). "The first lncRNA discovered, H19, has been found to participate in the regulation of diverse biological processes, including the pathogenesis of stomach adenocarcinoma." (PMID 36090894, 2022). "In this study, we established a prognostic model and nomogram for stomach adenocarcinoma by combining the expression level of H19 with traditional indices, which showed the value of H19 in predicting the survival rates of patients." (PMID 36090894, 2022).
gout (2 papers, 2023 to 2025). A condition characterized by painful swelling of the joints, which is caused by deposition of urate crystals. "Clinical research has demonstrated that the Huangqin Qingrechubi capsule significantly enhances lipid metabolism disorders and inflammatory responses in patients with gouty arthritis by modulating the lncRNA H19/APN/PI3K/AKT pathway, thereby effectively mitigating gout symptoms." (PMID 41255527, 2025).
gynecologic cancers (2 papers, 2021 to 2024). "Moreover, H19 has potential as a diagnostic and prognostic biomarker for gynecologic cancers, with its expression levels correlating with clinical parameters and patient outcomes." (PMID 38166752, 2024). "Understanding the functional roles of H19 in gynecologic cancers is crucial for the development of targeted therapeutic strategies and personalized treatment approaches." (PMID 38166752, 2024). "We further provide various perspectives on the association of some lncRNAs, i.e., HOTAIR, NEAT1, H19, MALAT1, and MEG3, in terms of invasion, proliferation, metastasis, apoptosis, and drug resistance of breast and gynecological cancers based on recent discoveries." (PMID 34885213, 2021). "In this article, we present a summary of the progress on ascertaining the biological functions of five lncRNAs (HOTAIR, NEAT1, H19, MALAT1, and MEG3) in female-oriented cancers, including breast and gynecological cancers, with the perspective of carcinogenesis, cancer proliferation, and metastasis." (PMID 34885213, 2021). "Therefore, in this article, we highlight the role of various lncRNAs and specifically five lncRNAs—HOTAIR, NEAT1, H19, MALAT1, and MEG3—in cancers unique to women, including breast and gynecological cancers." (PMID 34885213, 2021).
head and neck paraganglioma (2 papers, 2009 to 2022). A benign or malignant extra-adrenal paraganglioma arising from paraganglia in the head and neck. "In line with this hypothesis, recently H19, a paternally imprinted gene on 11p15, has been put forward as the tumor suppressor gene responsible for the parent-of-origin dependent inheritance in SDHD -linked head and neck paragangliomas." (PMID 19432956, 2009).
head and neck squamous cell carcinoma (2 papers, 2020 to 2022). A squamous cell carcinoma that arises from any of the following anatomic sites: lip and oral cavity, nasal cavity, paranasal sinuses, pharynx, larynx, and salivary glands. "In GEPIA, with RP11-54H7.4, MIR31HG, LINC00152, and LINC00511 being upregulated and H19, CTD-2545M3.8, RP11-760H22.2, and RP4-791M13.3 being consistently downregulated in head and neck squamous cell carcinoma (HNSC)." (PMID 32923393, 2020).
hydatidiform mole (2 papers, 2013 to 2017). A gestational trophoblastic disorder characterized by marked enlargement of the chorionic villi, hyperplasia of the villous trophoblastic cells and hydropic changes. "Complete hydatidiform moles (CHM) showed high-level expression of H19 from the paternal allele, while choriocarcinomas developing from CHMs had reduced numbers of H19-positive cells." (PMID 23711233, 2013).
inflammatory bowel disease (2 papers, 2023 to 2025). A spectrum of small and large bowel inflammatory diseases of unknown etiology. "Literature reports indicate that lncRNA H19 is significantly upregulated in inflammatory bowel disease and is closely associated with impaired intestinal barrier function, potentially serving as a diagnostic biomarker for IBD." (PMID 41312366, 2025). "In this study, we concluded that lncRNA H19 and its precursor miR-675-5p are overexpressed in inflammatory bowel disease, promising to be used as noninvasive, reliable biomarkers for IBD diagnosis." (PMID 37716920, 2023).
Intracranial Aneurysm (2 papers, 2019 to 2022). "Polymorphisms on the H19 genomic locus have been associated with increased risk of developing intracranial aneurysms." (PMID 35946958, 2022). "H19 was found up-regulated in the intracranial aneurysm tissue as compared with the adjacent normal arterial tissue from the same patient." (PMID 35946958, 2022).
invasive breast carcinoma (2 papers, 2019 to 2022). A carcinoma that infiltrates the breast parenchyma. "Aberrant hypermethylation of H19, a lncRNA has been observed in invasive breast carcinoma when compared to normal breast tissues, where tumor suppressive functions of H19 have been suggested." (PMID 36185256, 2022). "Furthermore, significant overexpression of H19 has been observed in either ductal carcinoma in situ (DCIS) or invasive breast cancer (IBC) compared with H19 expression in normal breast tissues (P < 0.05)." (PMID 31340867, 2019).
juvenile nasopharyngeal angiofibroma (2 papers, 2017 to 2018). "Furthermore, the IGF2/H19 imprinting changes were correlated with juvenile nasopharyngeal angiofibroma (JNA)." (PMID 29416703, 2018). "Among 27 samples from patients with Juvenile Nasopharyngeal Angiofibroma (JNA), 8 of 22 samples (36.4%) exhibited H19 over-expression and 7 of 19 samples (36.8%) exhibited IGF2 over-expression." (PMID 27802187, 2017).
laryngeal carcinoma (2 papers, 2019 to 2024). Carcinoma that arises from the laryngeal epithelium. "In the context of EBV, associated primarily with laryngeal cancer, the high expression of lncRNA H19 in EBV-positive individuals is significantly correlated with the occurrence of laryngeal cancer, likely via the transcriptional repressor EZH2 regulation." (PMID 38542512, 2024).
laryngeal squamous cell carcinoma (2 papers, 2019 to 2025). A squamous cell carcinoma that arises from the larynx. "Another study demonstrated the role of H19 in larynx squamous cell carcinoma and showed that H19 suppressed the activity of miR-148a-3p, and then enhanced the expression of the target gene DNMT1, which promoted proliferation, migration, and invasion of larynx squamous cell carcinoma cells." (PMID 31632488, 2019).
left ventricular hypertrophy (2 papers, 2021 to 2023). Enlargement of the LEFT VENTRICLE of the heart. "In the cardiac settings, H19 confers protection against left ventricular hypertrophy and ischemia." (PMID 34050133, 2021).
leiomyosarcoma (2 papers, 2020 to 2023). An uncommon, aggressive malignant smooth muscle neoplasm, usually occurring in post-menopausal women. "Combined with the idea that single nucleotide polymorphisms (SNPs) of H19 are related to a growing risk of leiomyosarcoma and tumor size, these findings indicate an essential role for H19 in the pathogenesis of UFs." (PMID 37507391, 2023).